PLK1 (polo like kinase 1)
Diseases named in the same sentence as PLK1 in open-access papers (continued):
Sharing a sentence is not in itself a finding about the gene and the disease.
thyroid tumor (3 papers, 2004 to 2018). A benign or malignant neoplasm affecting the thyroid gland. "Of note, our study identified MASTL as a novel mitotic machinery target in thyroid tumor, in addition to PLK1 and AURKs, both overexpressed and proposed as therapeutic targets in ATC." (PMID 26431489, 2015). "However, our findings are sharply in contrast with those in other carcinomas, and the physiological significance of PLK1 in thyroid tumours seems complicated." (PMID 14735186, 2004).
uterine cancer (3 papers, 2021 to 2024). Primary or metastatic malignant neoplasm involving the uterine corpus and/or the cervix. "In mouse xenograft models, we demonstrate that the O-GlcNAc–deficient PLK1-T291A and PLK1-T291N mutants enhance uterine carcinoma in animals." (PMID 36626982, 2023). "Through The Cancer Genome Atlas (TCGA) and xenograft analysis, we further correlate our biochemical and cytological studies with pathological consequences: T291A and T291N mutations and PLK1 upregulation promote uterine carcinoma." (PMID 36626982, 2023). "As T291N is a mutant involved in uterine carcinoma in TCGA, we investigated the correlation between PLK1 and uterine cancer." (PMID 36626982, 2023).
/T-cell lymphoma (2 papers, 2021 to 2023). "In this investigation, Spearman correlation analysis was initiated to ascertain the connection between PLK1 and p-PLK1 expression and the Ki-67 proliferation index among 40 cases of NK/T-cell lymphoma." (PMID 38037110, 2023). "The expression levels and active phosphorylation levels of PLK1 were significantly increased in NK/T cell lymphoma, and patients with overexpression of PLK1 and p-PLK1 had a poorer prognosis." (PMID 38037110, 2023). "In conclusion, the study demonstrated significantly elevated expression levels of PLK1 and its phosphorylation activity in NK/T-cell lymphoma compared to the control group." (PMID 38037110, 2023).
airway hyperresponsiveness (2 papers, 2019 to 2022). "PLK1, a serine/threonine-protein kinase, contributes to reducing airway resistance and airway hyperresponsiveness in asthmatic mice by regulating vimentin phosphorylation at Ser-56." (PMID 36393974, 2022).
anaplastic thyroid cancer (2 papers, 2012 to 2020). "In the present study, we first examined the relationship among PLK1 expression and clinical stage and lymphatic metastasis in undifferentiated thyroid carcinoma tissue." (PMID 23226764, 2012). "The expression of the PLK1 protein in 36 patients with anaplastic thyroid carcinoma was detected by immunohistochemical staining." (PMID 23226764, 2012). "The PLK1 gene is known to play an important regulatory role in the cell proliferation of undifferentiated thyroid carcinoma." (PMID 23226764, 2012). "In conclusion, the expression of PLK1 was found to be increased in anaplastic thyroid carcinoma and was correlated with clinical stage, lymph node metastasis and prognosis." (PMID 23226764, 2012). "The aim of this study was to observe the regulatory action of the polo-like kinase 1 (PLK1) gene in the invasion of anaplastic thyroid carcinoma cells and investigate its mechanisms." (PMID 23226764, 2012). "It was observed that the suppression of PLK1 activity decreased the survival rate of undifferentiated thyroid carcinoma cells significantly." (PMID 23226764, 2012). "In conclusion, PLK1 expression was upregulated in undifferentiated thyroid carcinoma and correlated with clinical stage, lymphatic metastasis and tumor prognosis." (PMID 23226764, 2012). "PLK1 siRNA suppressed the cell invasion of undifferentiated thyroid carcinoma, and CD44v6, MMP-2 and MMP-9 contributed to the regulation of cell invasion of undifferentiated thyroid carcinoma via PLK1." (PMID 23226764, 2012). "The expression of PLK1 in anaplastic thyroid carcinoma samples (67.5±10.6%) was significantly higher compared to that in cancer-adjacent samples (0.65%±0.12%; P<0.01)." (PMID 23226764, 2012). "The effect of PLK1 RNAi on the invasiveness of undifferentiated thyroid carcinoma ARO cells was then investigated." (PMID 23226764, 2012). "In addition, PLK1 expression correlated with clinical stage, lymphatic metastasis and prognosis of undifferentiated thyroid carcinoma." (PMID 23226764, 2012). "Additionaly, PLK1 siRNA was found to inhibit the invasion of anaplastic thyroid carcinoma cells." (PMID 23226764, 2012). "Therefore, PLK1 may become a molecular target for the treatment of undifferentiated thyroid carcinoma." (PMID 23226764, 2012). "The synergistic activity of PLK1 and PI3K inhibition combination has been recently reported in anaplastic thyroid cancer models and was likely to be due to a reducing mitotic slippage and endoreduplication." (PMID 32183025, 2020). "Therefore, PLK1 gene therapy may be a promising treatment for undifferentiated thyroid carcinoma." (PMID 23226764, 2012).
anemia (2 papers, 2020 to 2024). A reduction in the number of red blood cells, the amount of hemoglobin, and/or the volume of packed red blood cells. "Although PLK1 inhibitors have emerged as promising therapeutic agents for cancer, their use has been linked to significant anemia in a subset of patients, yet the underlying mechanisms remain poorly understood." (PMID 39763588, 2024). "Mechanistically, PLK1 deficiency primarily induces cell cycle arrest at the G2/M phase, triggering apoptosis and contributing to anemia." (PMID 39763588, 2024). "GSK461364, another ATP-competitive and selective PLK1 inhibitor, demonstrated antiproliferative activity across multiple tumor cell lines, though it also caused anemia and other blood disorders in clinical trials." (PMID 39763588, 2024). "In vivo studies further confirmed that PLK1 inhibitors cause severe anemia in mice, disrupting bone marrow (BM) hematopoietic stem cell homeostasis." (PMID 39763588, 2024). "Elucidating the mechanisms by which PLK1 inhibition causes anemia provides valuable insights for the prevention and treatment of anemia in clinical settings, while also offering new strategies for the development of cancer therapeutics and combinatory treatments." (PMID 39763588, 2024). "Overall, our findings underscore the critical role of PLK1 in erythropoiesis and shed light on the mechanisms underlying PLK1 inhibitor-induced anemia, providing essential guidance for developing strategies to prevent and manage anemia in clinical applications of PLK1-targeted therapies." (PMID 39763588, 2024). "Despite the widespread application of PLK1-targeted therapies in cancer trials, anemia remains a common complication." (PMID 39763588, 2024). "Multiple preclinical studies on PLK1 inhibitors have shown that different inhibitors lead to significant anemia." (PMID 39763588, 2024). "In vivo, administration of PLK1 inhibitors in mice induced severe anemia, as evidenced by a marked reduction in red blood cells and hemoglobin levels." (PMID 39763588, 2024). "These novel findings not only clarify the effects of PLK1 inhibition on erythropoiesis but also provide important theoretical support for understanding anemia as a side effect of PLK1 inhibitor therapy in clinical settings." (PMID 39763588, 2024). "In conclusion, PLK1-inhibitor treated mice exhibit pronounced anemia and splenomegaly, accompanied by extramedullary erythropoiesis." (PMID 39763588, 2024). "Although PLK1-targeted therapies are widely used in clinical trials for cancer treatment, anemia remains a common complication." (PMID 39763588, 2024). "Anemia can substantially compromise the therapeutic efficacy of PLK1 inhibitors in oncology." (PMID 39763588, 2024). "In summary, our research systematically revealed the critical regulatory role of PLK1 in erythroid development, demonstrating that its inhibitors induce anemia by affecting the proliferation, differentiation, enucleation, apoptosis, and cell cycle of erythroid precursor cells." (PMID 39763588, 2024). "To explore whether the severe anemia observed in PLK1 inhibitor-treated mice stemmed from disruptions in HSC homeostasis or the committed differentiation of hematopoietic progenitors, we examined the impact of PLK1 on both HSCs and progenitor cell function." (PMID 39763588, 2024).
atherosclerosis (2 papers, 2024). A disease characterized by the build-up of fatty material and calcium deposition in the arterial wall resulting in partial or complete occlusion of the arterial lumen. "Recent studies have explored the role of circular RNAs (circRNAs) in atherosclerosis, revealing key players such as CircRNA_102541 and PLK1, which exhibit overexpression, while miR-296-5p levels were reduced in atherosclerosis specimens." (PMID 38474233, 2024).
childhood cancers (2 papers, 2012 to 2017). "Based on this result and the overexpression of PLK1 in childhood cancers, PLK1 was selected for further evaluation." (PMID 29228610, 2017).
Cirrhosis (2 papers, 2014 to 2023). A chronic disorder of the liver in which liver tissue becomes scarred and is partially replaced by regenerative nodules and fibrotic tissue resulting in loss of liver function. "Taken together, in the present study, we have demonstrated that upregulation of PLK1 expression may be an early diagnostic marker for the canceration of cirrhosis and the development of HCC, but less correlation between PLK1 and metastasis was observed." (PMID 25019081, 2014). "In patients with hepatitis C and Child-Pugh A cirrhosis, PLK1 expression was higher in patients with poor prognosis (P < 0.01) and predicts death, progression to advanced cirrhosis, and development of HCC over 10 yr (GSE15654)." (PMID 37648284, 2023). "We found that there is similar expression of PLK1 in cirrhosis with 3 paired HCC tissues and only 2 cases were lower than paired HCC tissues (data not shown)." (PMID 25019081, 2014). "More interesting is that, in 27 cases of cirrhosis from HCC, the expression of PLK1 in cirrhosis was positive either; moreover, 22 cases showed higher levels of PLK1 than that of cancer tissues (data not shown)." (PMID 25019081, 2014). "To investigate the role of PLK1 in human hepatocarcinogenesis, we determined its expression in normal human livers, HCCs, and surrounding cirrhosis tissues using immunohistochemistry." (PMID 25019081, 2014). "In addition, the similar elevated levels of PLK1 expression in HCCs and surrounding cirrhosis suggested that PLK1 can serve as the prognostic standard to judge the possibility of canceration of cirrhosis tissue." (PMID 25019081, 2014). "The difference of PLK1 expression in HCC nidus and surrounding cirrhosis tissues indicated that PLK1 may play an important role in HCC early development and its inhibition might contribute to the control of HCC." (PMID 25019081, 2014).
cyst (2 papers, 2020 to 2021). A sac-like closed membranous structure that may be empty or contain fluid or amorphous material. "Here we show that racemose larvae contain proliferative plk1-expressing cells in their bladder wall that drive continuous cyst growth." (PMID 33750965, 2021). "We assayed these 5 compounds (the mTOR inhibitor Everolimus, the Chk1 inhibitor AZD-7762, the Ikk inhibitor IMD-0354 and the Plk1 inhibitors Volasertib and Rigosertib) in our Matrigel-based 3D assay and found that all inhibited cyst growth." (PMID 32144367, 2020). "Cells expressing plk1 were present over the entire vesicular bladder wall but were concentrated at growth regions of developing buds, which is consistent with their essential role in cyst multiplication." (PMID 33750965, 2021).
cystadenoma (2 papers, 2004 to 2018). A benign or borderline cystic epithelial neoplasm arising from the glandular epithelium. "In cystadenomas, considerable expression of PLK1 was observed in three out of 17 cases (17.6%)." (PMID 14970859, 2004). "PLK 1 and PLK3 expression was low in normal ovarian surface epithelium and borderline tumours, with moderately higher expression levels in cystadenomas." (PMID 14970859, 2004).
cytomegalovirus infection (2 papers, 2016 to 2025). A herpesvirus infection caused by Cytomegalovirus. "Rock2, Ccl5, Plk1, Rel, and Ctnnb1 are mainly associated with inflammatory responses, including positive regulation of IκB kinase/NF-κB signalling and human cytomegalovirus infection." (PMID 41007634, 2025).
diabetic nephropathy (2 papers, 2023 to 2024). "PLK-1 is a key regulator of the cell cycle and cell division and its inhibition has been shown to reduce proteinuria in a diabetic nephropathy model." (PMID 36922538, 2023).
gallbladder cancer (2 papers, 2023). "PAIP1 promotes gallbladder cancer through regulating expression of PLK1." (PMID 37101794, 2023). "Correlation studies suggested that the expression of CEP55 in gallbladder cancer was significantly positively correlated with that of PLK1, indicating that CEP55 has potential as a molecular target for gallbladder cancer therapy like PLK1." (PMID 37274251, 2023). "It was worth noting that the mRNA levels of PLK1 and CEP55 were significantly upregulated in gallbladder cancer tissues than in adjacent tissues." (PMID 37274251, 2023). "Strikingly, previous studies demonstrated that PLK1 is highly expressed in GBC tissues, advances GBC progression, and exacerbates the prognosis of gallbladder cancer." (PMID 37274251, 2023). "It has been reported that PLK1 is upregulated in gallbladder cancer and is associated with poor prognosis in gallbladder cancer patients, while the role of CEP55 in gallbladder cancer has not been reported." (PMID 37274251, 2023). "In combined analysis, CEP55 was markedly positively correlated with PLK1 in gallbladder cancer, R = 0.557, confirming that CEP55 may play a vital role in the progression of gallbladder cancer as PLK1." (PMID 37274251, 2023).
hepatitis B (2 papers, 2023 to 2024). "Consistent with this, our data suggest that PLK1 may also contribute to HCC progression in patients with hepatitis B as we showed increased PLK1 expression in their livers." (PMID 37648284, 2023).
hepatitis C (2 papers, 2017 to 2023). "Similar to hepatitis C, patients with chronic hepatitis B have higher PLK1 expression in their livers than uninfected patients (GSE83148)." (PMID 37648284, 2023). "PLK1 expression is increased in patients with hepatitis B or hepatitis C, but not in patients with MAFLD, suggesting a virus-specific effect that may contribute to the development and progression of HCC in patients with viral hepatitis." (PMID 37648284, 2023).
intestinal tumors (2 papers, 2018 to 2025). "Conversely, inhibition of PLK1 increased intestinal tumors in two independent ApcMin/+ mouse models." (PMID 41261855, 2025).
leiomyosarcoma (2 papers, 2016 to 2025). An uncommon, aggressive malignant smooth muscle neoplasm, usually occurring in post-menopausal women. "In 2012, Shan and colleagues reported increased expression of PLK1 and its upstream regulator Aurora A kinase in uterine leiomyosarcomas, a neoplastic lesion involving SMCs of the uterine myometrium." (PMID 26820885, 2016). "Targeting and inhibition of the PLK1 upstream kinase, Aurora A, in the leiomyosarcomas cells decreased the proliferation and induced apoptosis in these malignant cells." (PMID 26820885, 2016).
malignant pleural mesothelioma (2 papers, 2017 to 2021). A malignant neoplasm that arises from mesothelial cells in the pleura and shows a diffuse growth pattern. "Next, we evaluated the therapeutic potential of co‐targeting PLK1 and FGFR in KRAS‐mutant cancer cells, with KRAS wild‐type cancer cells, malignant pleural mesothelioma (MPM) cells, and non‐transformed normal cells tested in parallel for comparison." (PMID 34369083, 2021).
metastatic colorectal cancer (2 papers, 2024 to 2025). "A recent phase I trial reported a 44% partial response rate of onvansertib, a PLK1 inhibitor, in the treatment of patients with KRAS-mutated metastatic colorectal cancer, indicating that PLK1 inhibitor might be suitable for the treatment of this specific subtype of cancer." (PMID 40852028, 2025).
metastatic prostate carcinoma (2 papers, 2023 to 2025). A carcinoma that arises from the prostate gland and has spread to other anatomic sites. "Notably, while PSAT1 and PSPH exhibited no change in expression by PLK1, PHGDH showed a significant decrease in our experimental models of advanced metastatic prostate cancers." (PMID 40475404, 2025).
neurofibroma (2 papers, 2017 to 2025). An intraneural or extraneural neoplasm arising from nerve tissues and neural sheaths. "Subsequent analyses demonstrated that PLK1 mRNA and protein levels were significantly elevated in MPNSTs compared to benign neurofibromas and normal Schwann cells, indicating a likely dependency on PLK1 in malignant cells." (PMID 41294711, 2025). "PLK1,RRM1, and RRM2 mRNA levels were increased in MPNST compared to benign neurofibroma tissue, and the protein level of PLK1 was increased in the MPNST cell lines compared to normal Schwann cells, indicating an increased dependence on these drug targets in malignant cells." (PMID 28556483, 2017).
Obesity (2 papers, 2019 to 2023). Accumulation of substantial excess body fat. "Interestingly, the obesity-related factors insulin and leptin have been reported to induce an increase in the expression of PLK1." (PMID 37447165, 2023). "Active PLK1-driven metastasis is also amplified by TGF-β signaling, whose activity is increased in advanced tumors as well as in obesity." (PMID 37447165, 2023).
Oral Squamous Cell Carcinoma (2 papers, 2022 to 2024). "Polo-like-kinase-1 (PLK-1) is a serine/threonine kinase that regulates the cell cycle and acts as an oncogene in multiple cancers, including oral squamous cell carcinoma (OSCC)." (PMID 38540116, 2024).
schizophrenia (2 papers, 2017 to 2024). A major psychotic disorder characterized by abnormalities in the perception or expression of reality. "However, although PCM-1 and AHI1 are associated with schizophrenia, there are no observations of implication of either Plk1 or Rab8, into pathogenesis of schizophrenia." (PMID 28125008, 2017).
Thrombocytopenia (2 papers, 2025). A reduction in the number of circulating thrombocytes. "We therefore hypothesized that megakaryocyte progenitors in subsets of MDS patients with thrombocytopenia would elevate expression levels of mitotic genes, including AURKA, AURKB, and PLK1, which in turn would promote cytokinesis/cell cycling rather than endomitosis." (PMID 40813622, 2025).
adenovirus infection (1 paper, 2009). "Interestingly, when Plk1 was over-expressed in cardiac myocytes by adenovirus infection, it was not able to promote cell cycle progression, as determined by cell number and percent binucleation." (PMID 19707596, 2009).
allergic asthma (1 paper, 2019). A asthma with a basis in a pathological type I hypersensitivity reaction. "Thus, these investigations suggest that Plk1 is involved in the progress of airway smooth muscle layer thickening and hyperresponsiveness in allergic asthma." (PMID 31101859, 2019). "Considering the role Plk1 in paxillin phosphorylation on Ser-272 and division in the cell model, it is likely that Plk1 contributes to airway smooth muscle layer thickening in allergic asthma in part by affecting paxillin phosphorylation and smooth muscle cell division." (PMID 31101859, 2019). "The results support the concept that Plk1-mediated airway smooth muscle thickening in allergic asthma results from the effects of Plk1 on cell division, but not from allergic airway inflammation." (PMID 31101859, 2019).
anaplastic carcinoma (1 paper, 2004). "In follicular tumours and anaplastic carcinoma, PLK1 overexpression was not a common event and only 5.9% of follicular adenoma, 7.1% of follicular carcinoma, and 11.8% of anaplastic carcinoma overexpressed this protein." (PMID 14735186, 2004). "Another interesting finding is the frequent lack of PLK1 expression in anaplastic carcinoma." (PMID 14735186, 2004).